RNF170 (ring finger protein 170)
Description:
E3 ubiquitin-protein ligase that plays an essential role in stimulus-induced inositol 1,4,5-trisphosphate receptor type 1 (ITPR1) ubiquitination and degradation via the endoplasmic reticulum-associated degradation (ERAD) pathway. Also involved in ITPR1 turnover in resting cells. Selectively inhibits the TLR3-triggered innate immune response by promoting the 'Lys-48'-linked polyubiquitination and degradation of TLR3.
Synonyms: DKFZP564A022; ADSA; SNAX1; SPG85
Tractability: Antibody: UniProt predicts a signal peptide or a membrane-spanning region. PROTAC: ubiquitination databases record sites on it; its protein half-life has been measured.
Gene: Protein-coding gene on chromosome 8 (42,849,637 to 42,897,290, reverse strand). Ensembl gene ENSG00000120925.
Subcellular location: Endoplasmic reticulum membrane
Gene Ontology:
Molecular function: protein binding; ubiquitin protein ligase activity
Biological process: negative regulation of toll-like receptor 3 signaling pathway; protein K48-linked ubiquitination; protein ubiquitination
Cellular component: endoplasmic reticulum membrane
Genetic constraint (gnomAD): Loss-of-function variants: 5 observed, 15.83 expected, observed/expected ratio (o/e) 0.32, 90% interval 0.16 to 0.66. The upper end of that interval is the gene's LOEUF score, 0.66, which puts it in group 2 of 6, group 1 being the genes least tolerant of losing a copy. Missense variants: 166 observed, 255.8 expected, observed/expected ratio (o/e) 0.65, 90% interval 0.57 to 0.74. Synonymous variants: 75 observed, 87.01 expected, observed/expected ratio (o/e) 0.86, 90% interval 0.71 to 1.04.
Homologues: Orthologues: macaque RNF170 (99% identical), chimpanzee RNF170 (99% identical), rabbit RNF170 (98% identical), dog RNF170 (97% identical), guinea pig RNF170 (96% identical), pig RNF170 (96% identical), rat Rnf170 (91% identical), mouse Rnf170 (91% identical), tropical clawed frog rnf170 (70% identical), zebrafish rnf170 (64% identical), Caenorhabditis elegans Y38F1A.2 (31% identical).
Diseases named in the same sentence as RNF170 in open-access papers:
RNF170 is named in the same sentence as 26 diseases in open-access papers, as found by Europe PMC text mining. Sharing a sentence is not in itself a finding about the gene and the disease. The quoted sentences say what the papers report.
cerebellar ataxia (4 papers, 2019 to 2022). A neurological syndrome characterized by clumsy and uncoordinated movement of the limbs, trunk, and cranial muscles. "Recessive RNF170 mutations have recently been confirmed as a cause of HSP **, but a heterozygous mutation in RNF170 (p.Arg199Cys) was found to cause autosomal dominant late-onset progressive sensory ganglionopathy as a cerebellar ataxia, neuropathy, and vestibular areflexia syndrome (CANVAS) mimic." (PMID 33646413, 2021). "Phenotypically, we find that autosomal recessive HSP caused by RNF170 deficiency is characterized by infancy onset progressive spastic paraplegia, accompagnied by optic atrophy of variable severity and in some cases by cerebellar ataxia and subclinical involvement of the central sensory tracts." (PMID 31636353, 2019). "The clinical features of the four reported RNF170‐HSP families were infantile onset, complicated HSP with varying degrees of optic atrophy and cerebellar ataxia." (PMID 34734492, 2021).
microcephaly (3 papers, 2019 to 2023). A congenital or acquired developmental disorder in which the circumference of the head is smaller than normal for the person's age and sex. "Knockdown of rnf170 resulted in developmental defects visible by 48 hpf, these include microphthalmia, microcephaly, and loss of motility." (PMID 31636353, 2019).
autosomal dominant sensory ataxia 1 (1 paper, 2021). Any hereditary ataxia in which the cause of the disease is a mutation in the RNF170 gene. "A missense mutation in RNF170, a ubiquitin E3 ligase gene, has been related to autosomal dominant sensory ataxia 1, which was found in two families from Canada." (PMID 33671313, 2021).
Cerebellar atrophy (1 paper, 2019). Cerebellar atrophy is defined as a cerebellum with initially normal structures, in a posterior fossa with normal size, which displays enlarged fissures (interfolial spaces) in comparison to the foliae secondary to loss of tissue. "Saccadic pursuit in families A and D as well as upper limb ataxia, ataxic gait, and cerebellar atrophy in B.3 and B.4 indicate that the cerebellum can be variably affected in RNF170-associated disease." (PMID 31636353, 2019).
hereditary spastic paraplegia (1 paper, 2019). Hereditary spastic paraplegias (HSP) comprise a genetically and clinically heterogeneous group of neurodegenerative disorders characterized by progressive spasticity and hyperreflexia of the lower limbs. "Here, the authors identify in four families with hereditary spastic paraplegia biallelic mutations in RNF170 that associate with increased basal levels of IP3 receptors." (PMID 31636353, 2019).
neuroblastoma (1 paper, 2019). Neuroblastoma (NB) is the most common solid, extracranial childhood tumor. "Using CRISPR/Cas9, we introduced a homozygous 35-bp frameshift mutation into the neuroblastoma cell line SH-SY5Y; loss of RNF170 protein expression was confirmed by western blot." (PMID 31636353, 2019).
spastic ataxia (1 paper, 2021). "Spastic ataxias refer to disorders in which most patients have a clinical presentation with equal contribution of pyramidal and cerebellar involvement such as in spastic ataxia of Charlevoix-Saguenay, and in SPG7, SAX2, SPG43 and RNF170 mutation carriers ((Synofzik and Schüle, 2017)." (PMID 34901147, 2021).
viral infection (1 paper, 2021). "Although Rnf170−/− mice and their derived myeloid cells produced more cytokines upon TLR3 stimulation, and were consequently more resistant to viral infection, it remains unknown how RNF170 is itself activated." (PMID 33808506, 2021).
neurodegenerative disease (2 papers, 2022 to 2023). A disorder of the central nervous system characterized by gradual and progressive loss of neural tissue and neurologic function. "The RNF170 homozygous knockout mice developed sensory and gait abnormalities in old age, suggesting that HSP was a neurodegenerative disease." (PMID 40225166, 2023).
RNF170 also shares sentences with these, for which no sentence is quoted: infection (17 papers); abscess (6); microphthalmia (3); bacteremia (2); neuropathy (2); optic atrophy (2); Sepsis (2); Ataxia (1); cytomegalovirus infection (1); infectious disease (1); mastitis (1); myeloma (1); sensory ataxia (1); Spastic paraplegia (1); staphylococcal infection (1); staphylococcus infections (1); ventilator-associated pneumonia (1).